IL7R (interleukin 7 receptor)
Diseases named in the same sentence as IL7R in open-access papers (continued):
Sharing a sentence is not in itself a finding about the gene and the disease.
leukemia (continued). "Full transformation associates with transcriptional upregulation of oncogenes such as Myc or Bcl2, downregulation of tumor suppressors such as Ikzf1 or Arid2, and major IL-7R signaling upregulation (involving JAK/STAT5 and PI3K/mTOR), required for leukemia cell viability." (PMID 34907175, 2021). "The realization that IL-7R/IL-7 signaling directly contributes to T-ALL LIC activity has important clinical implications, as new therapeutic developments against leukemia mostly rely on molecular targets of LIC cells, which are finally responsible of disease relapse." (PMID 33081391, 2020). "Given the importance of IL7R in CNS leukemia, IL7R-mediated CNS infiltration could be of particular importance for E2A-PBX1 positive leukemia." (PMID 31970588, 2020). "IL-7 and IL-7Rα have also been found to interact with Janus kinase (JAK), leading to JAK phosphorylation and activation of downstream pathways such as signal transducer and activation proteins (STAT5) that can further lead to the proliferation of leukemia cells." (PMID 34830969, 2021). "Because IL7R mutant leukemias exhibited clear upregulation of mTOR signaling, we administered the clinical-grade dual PI3K and mTOR inhibitor dactolisib and found it had a striking impact on the frequency of leukemia cells in the blood, significantly prolonging the survival of transplanted mice." (PMID 34907175, 2021). "Quantitative PCR analysis of Notch targets from total BM cells of leukemia mice revealed upregulations of Hes1, Deltex1 (Targets of Notch signaling) and IL7Rα compared to normal BM cells, in line with the reports that upregulation of IL7Ra is often observed in human T-ALL cells from patients." (PMID 33996794, 2021). "Importantly, one of seven transplanted IL7R mutant precursors transduced with Kras Q61H developed leukemia, whereas none of the controls showed any signs of leukemia development." (PMID 34907175, 2021). "Thus, anti-IL7R antibodies may provide alternative treatment options for ALL in general and may suppress incurable drug-resistant leukemia forms." (PMID 32581241, 2020). "Thus, a network linking MEF2C, IL7R, STAT5 and AUTS2 may play a role in two cellular contexts: T-cell differentiation/leukemia and brain development/autism-related disorders." (PMID 27322685, 2016). "Finally, although there is anecdotal evidence that high IL7R expression correlates with increased leukemia propagating/stem cell activity, the impact of IL7R activation in regulating the overall frequency of leukemia propagating cells within T-ALL is currently not known." (PMID 35581375, 2022). "While increased signaling in homozygous versus heterozygous IL7R mutant leukemias may potentially result from increased expression of the mutant form and/or absence of the wild-type IL7R, the end-result is markedly increased signaling and increased oncogenic potential." (PMID 34907175, 2021). "However, NICD YS-derived T-cells failed to progress leukemia despite successful NICD induction and higher IL7R expression." (PMID 33996794, 2021).
multiple sclerosis (58 papers, 2008 to 2025). A progressive autoimmune disorder affecting the central nervous system resulting in demyelination. "In MS, genetic variations in the IL-7R gene are linked to disease susceptibility, and IL-7 impacts the survival and differentiation of T cell subsets involved in multiple sclerosis pathogenesis." (PMID 40313966, 2025). "A similar mechanism has been reported in a study linking the c.731C IL7R polymorphism to susceptibility to multiple sclerosis (MS)." (PMID 38587703, 2024). "As a proof-of-principle for evaluating ASE, we selected polymorphism rs6897932, associated with multiple sclerosis susceptibility and located in exon 6 of IL7R, 817 base pairs from the 5′ transcript end (NM_002185.5: c.818C/T)." (PMID 37696578, 2023). "Single-nucleotide polymorphism (SNP) of IL7R gene, such as rs6897932, rs3194051 and rs987106, has been associated with clinical severity in multiple sclerosis, hepatitis C and human immunodeficiency virus infection." (PMID 35907923, 2022). "Previous studies found the notable relevance of IL7R allele polymorphism with the onset age of multiple sclerosis." (PMID 36561317, 2022). "For example, the “suggestive” AS association with rs6897932 in IL7R mirrored similar genome-wide significant associations of IL7R with multiple sclerosis and primary biliary sclerosis." (PMID 33746951, 2021). "The first MS GWAS was performed on 931 family trios and identified variants in the interleukin-7 receptor (IL7R) and in the interleukin-2 receptor (IL2RA) loci, again pointing to the crucial role played by the immune system." (PMID 33335478, 2020). "Studies showed that the IL7R allele polymorphism was associated with an increased risk of multiple sclerosis (MS), and there was a significant association between the IL7R promoter polymorphisms and the age of onset of MS." (PMID 32746852, 2020). "More importantly, the authors showed a significant increased risk in multiple sclerosis when rs2523506 interacts with a risk variant of IL7R (rs6897932)." (PMID 30060490, 2018). "The rs6897932 SNP in the transmembrane region of the IL-7Rα increases the risk of developing multiple sclerosis, ulcerative colitis, and sarcoidosis." (PMID 29456530, 2018). "A driver of increased risk in multiple sclerosis is the soluble form of interleukin-7 receptor (IL-7R, encoded by IL7R)." (PMID 30060490, 2018). "IL7R plays a role in the immune system and is implicated in multiple sclerosis, whereas PKHD1 influences kidney and liver functions." (PMID 27120335, 2016). "Previous meta-analysis and genome-wide association studies showed that genetic variation in the IL7R gene is associated with ulcerative colitis, multiple sclerosis, primary biliary cirrhosis and type 1 diabetes." (PMID 26566388, 2015). "Last, DLA II and IL7R both have been implicated in human inflammatory diseases of the central nervous system such as multiple sclerosis, suggesting that similar pharmacotherapeutic targets across species should be investigated." (PMID 25393235, 2014). "We also note that IL7R (interleukin-7 receptor subunit alpha), polymorphisms of which have been associated with risk in multiple sclerosis, is upregulated (FC = 1.7, qSAM = 0%, p < 0.005)." (PMID 22027401, 2011). "Several genetic and functional studies have associated genetic variants of IL7R gene with susceptibility to multiple sclerosis." (PMID 18431485, 2008). "IL7R expression disruption contributes to immunopathologies, as demonstrated by severe immunodeficiencies, and loss-of-function variants in humans are strongly associated with risk for multiple sclerosis (MS)." (PMID 37446229, 2023). "In addition, RNA helicase DDX39B is a potent activator promoting the inclusion of IL7R exon 6 and consequently, a suppressor of the sIL7R protein isoform, which has been associated with an increased risk of multiple sclerosis." (PMID 31046669, 2019).
multiple sclerosis (continued). "However, single nucleotide polymorphisms (SNPs) of the IL-7Rα were associated with an increased risk of developing type 1 diabetes and multiple sclerosis." (PMID 26983628, 2016). "The IL7Rα gene is unequivocally associated with susceptibility to multiple sclerosis (MS)." (PMID 24147013, 2013). "Interleukin Receptor 7 (IL7R) identified as significant in the multiple sclerosis possible comorbidity was shown to be significantly upregulated by 2.11 log-fold change (logFC) in SARS." (PMID 33924631, 2021). "Il7r is involved in the pathogenesis of demyelination in both patients with multiple sclerosis (MS) and animal models of experimental autoimmune encephalomyelitis." (PMID 29449560, 2018). "Dysregulated IL-7/IL-7R signaling and numerous increased risk association with IL-7R polymorphisms have been observed in patients suffering from IMID (e.g. multiple sclerosis, type 1 diabetes, rheumatoid arthritis, inflammatory bowel diseases)." (PMID 31225460, 2018). "A SNP within the exon 6 of IL7R has been identified in patients with multiple sclerosis that leads to skipping of exon 6 leading to increased levels of soluble IL-7Rα." (PMID 26703587, 2015). "In humans, IL-7 and its receptor (IL-7R) are increased in diseases characterized by inflammation such as atherosclerosis, rheumatoid arthritis, psoriasis, multiple sclerosis, and inflammatory bowel disease." (PMID 23057802, 2012). "IL-7R signaling is vital for the survival and expansion of pathogenic T helper type 17 (TH17) cells, which are key players in autoimmune inflammation, as seen in multiple sclerosis." (PMID 40313966, 2025). "IL7/IL7R signaling may play a role in various autoimmune or inflammatory diseases including multiple sclerosis, type 1 diabetes mellitus, RA, and ulcerative colitis." (PMID 38401037, 2024). "Il7r is involved in the pathogenesis of neurodegenerative disorders, such as multiple sclerosis." (PMID 29449560, 2018). "Interleukin 7 receptor (IL-7R) has been associated with the pathogenesis of multiple sclerosis (MS), though the mechanisms are not clear." (PMID 28415697, 2017). "The anti-IL-7Rα monoclonal antibody PF-06342674 (RN168) developed from Pfizer has been tested in phase 1b in patients with multiple sclerosis (NCT02045732 ClinicalTrials.gov identifier) with the primary outcome to evaluate adverse side effects and pharmacokinetic–pharmacodynamic properties." (PMID 26983628, 2016). "The rs3194051 polymorphism, a tag SNP of IL7R haplotype 4 in European populations, has been associated with highest CD127 on CD4+ T-cell, higher frequencies of recent thymic emigrants, and lower plasma sCD127 levels in patients with multiple sclerosis." (PMID 26123260, 2015). "Additionally, altered expression of the genes encoding IL7Rα and its ligand, IL7, has been found in the cerebrospinal fluid of individuals with multiple sclerosis." (PMID 25393235, 2014). "Additionally, all genes in these regions were prioritized based on ENDEAVOUR gene prioritization with a training set of human multiple sclerosis genes, which resulted in prioritization of IL7R on chromosome 4 and FBXW7 on chromosome 15." (PMID 25393235, 2014). "Alterations in IL7R have not been associated with disease in dogs, but polymorphisms in IL7R have been demonstrated to contribute to non-MHC genetic risk in multiple sclerosis." (PMID 25393235, 2014). "Recent association studies in multiple sclerosis (MS) have identified and replicated several single nucleotide polymorphism (SNP) susceptibility loci including CLEC16A, IL2RA, IL7R, RPL5, CD58, CD40 and chromosome 12q13–14 in addition to the well established allele HLA-DR15." (PMID 20368992, 2010). "Similarly, SNP rs6897932 in a putative exonic splice enhancer in IL7R seems to affect exon 6 splicing, amounts of soluble versus membrane-bound IL7R and risks of multiple sclerosis and type 1 diabetes." (PMID 20948966, 2010).
multiple sclerosis (continued). "Finally, the finding that IL7R, in addition to DLA II, may be associated with NME development supports previous theories that NME and multiple sclerosis may have similar pathogenic mechanisms." (PMID 25393235, 2014). "This exon is skipped in approximately half of IL7R transcripts (median [IQR]: 45% [40–50%] in 30 controls, 50% [45–55%] in 23 multiple sclerosis patients)." (PMID 37696578, 2023). "Although a causal variant associated with IL7R has not been identified, this finding in Maltese dogs supports the hypothesis that NME and multiple sclerosis may share similar pathways for disease development." (PMID 25393235, 2014). "Mice lacking IL-7Rα have severe lymphopenia and are resistant to experimental autoimmune encephalomyelitis (EAE), a model for multiple sclerosis." (PMID 39380064, 2024).
COVID-19 (48 papers, 2020 to 2026). A disease caused by infection with severe acute respiratory syndrome coronavirus 2. "Impaired circulating innate lymphoid cells (ILCs) were reported in severe COVID-19 patients, and these could also be associated with defects in IL-7/IL-7R signaling." (PMID 34603318, 2021). "IL7R upregulation in both COVID-19 and DN suggests a possible connection between immune dysregulation and kidney injury, showing its importance as a marker regarding disease severity and progression." (PMID 41332907, 2025). "•PPI-identified hub genes IL7R/CD2/GZMA/CD3D/FCER1A diagnose COVID-19 and diabetic nephropathy with AUC>0.80, linking immune activation to tissue damage." (PMID 41332907, 2025). "For COVID-19, the AUCs of IL7R, CD2, GZMA, CD3D, and FCER1A were 0.925, 0.934, 0.905, 0.950, and 0.998, respectively." (PMID 41332907, 2025). "Strategies associated with identified biomarkers and therapeutic candidates, including interleukin-7 receptor-targeting strategies, offer the potential for improving clinical outcomes in patients with comorbid COVID-19 and DN." (PMID 41332907, 2025). "We found a significant reduction in IL-7R in neutrophils from COVID-19 patients compared with HCs and ward versus ICU-admitted patients." (PMID 39012145, 2024). "CD74, CIITA, CD3D and IL7R were downregulated in critically ill COVID-19 patients in accordance with the occurrence of altered monocyte and T lymphocyte responses." (PMID 36389738, 2022). "Mon HLA and Mon CD14 inside Delta samples differ in expression for the cytokine panel (CCL3, VEGFA, CCL5, CCL4, CXCR4, IL7R, CXCL8, and PF4) that have been found associated with COVID-19 severity and mortality." (PMID 36230912, 2022). "Profiling IL-2R and IL-7R subunit abundance of healthy controls and COVID-19 patients during acute infection (Acute), 6 months (6 M follow-up) and 12 months after clinical recovery (12 M follow-up) revealed prolonged changes in these receptors, most notably in the T cell compartment." (PMID 41310351, 2025). "Higher expression of SAS-1 (SAS-1high) likely tracked IChigh, as this signature comprised IC-related genes (e.g., CCR7, IL7R) and higher baseline expression of SAS-1 associated with lower all-cause mortality hazards during acute COVID-19 as well as lower all-cause mortality hazards in the FHS." (PMID 37311745, 2023). "Moreover, we performed further study with finding a similar high-low-high expression pattern of human SNHG1/VPS13D/IL7R/TCF7 in CD8 T cell subsets from PBMC samples of the convalescent COVID-19 patients." (PMID 33758164, 2021). "Considering our observations in the animal infection model, we questioned whether a differential in the expression level of GM-CSFR/IL-7R in neutrophils of COVID-19 patients or the plasma concentrations of GM-CSF and/or IL-7 may explain the reduction in the B cell population." (PMID 39012145, 2024). "Finally, our data showing the expression of IL-7R in cytotoxic monocytes are consistent with the presence of IL7R+ monocytes/macrophages in COVID-19 BALF, and further support the hypothesis that these cells are key players in the progress of the disease." (PMID 36263038, 2022). "We uncovered gene-regulatory mechanisms at disease loci with therapeutic implications, such as WARS1 in hypertension, IL7R in dermatitis and IFNAR2 in COVID-19." (PMID 40038547, 2025). "In a parallel analysis, the datasets from GSE152418 revealed pronounced differences in the expression of IL7R, CD2, CD3D and FCER1A when comparing COVID-19 samples to control samples." (PMID 41332907, 2025). "Performing this analysis for the COVID-19 patients demonstrated clear B- and T-cell clusters, defined by expression of TCF7, LEF1 (clusters 0 and 1), CD74, CD79A (clusters 2 and 3), IL7R (cluster 4) and CCL5, NKG7, GNLY (cluster 6)." (PMID 33884369, 2021).
COVID-19 (continued). "Notably, in severe/critical COVID-19 patients in the recovery stage, the proportion of CD14 monocytes (based on the expression of the marker genes CST3, LYZ, CD14) in PBMCs were elevated, but CD4 T cells (IL7R, LTB) were decreased, consistent with a previous report." (PMID 35046942, 2021).
viral infection (40 papers, 2009 to 2025). "Altogether, our findings provide a very detailed characterization of IL-2R and IL-7R distribution on human peripheral lymphocyte subsets at steady-state and following acute viral infection and cytokine stimulation." (PMID 41310351, 2025). "Further unbiased investigation into the most expressed genes per cluster revealed a plethora of genes previously reported in the context of viral infections, such as Il7r, Tcf7, Zeb2, Klrg1, Gzma, Gzmb, Gzmk, Vim, Lgals3, Tox, Lag3, Pdc1, Id3." (PMID 35185882, 2022). "During acute viral infections in mice, IL‐7Rα and KLRG1 together are used to distinguish the short‐lived effector cells (SLEC; IL‐7RαloKLRGhi) from the precursors of persisting memory cells (MPEC; IL‐7RαhiKLRG1lo)." (PMID 30883723, 2019). "During chronic viral infection and tolerization of self reactive T cells, continuous engagement between antigens and TCRs down–regulates the IL-7R expression on antigen specific T cells." (PMID 29272267, 2017). "Irreversible down-regulation of IL-7Rα also occurs in functionally “exhausted” T cells that accumulate during persistent viral infections, such as HIV or LCMV and, interestingly, high levels of IL-7 can be detected in the serum of AIDS patients." (PMID 22102903, 2011). "To investigate whether the trajectories of IL-2R and IL7-R expression during vaccination are recapitulated in the context of an acute viral infection, we compared these receptors in 25 healthy controls and 64 individuals with acute SARS-CoV-2 infection." (PMID 41310351, 2025). "Our Il7r distal enhancer deletion experiment demonstrated that cell state-specific enhancers could be an optimal way to precisely manipulate T cells after viral infection or vaccination." (PMID 39804040, 2025). "The increased levels of IL-7Rα on virus-specific CD8+ T cells from Selplg-/- mice compared to WT mice suggested the possibility of altered differentiation of CD8+ T cells during the course of viral infection." (PMID 34326837, 2021). "Although IFN-γ can directly increase the abundance of CD8 T cells during viral infection, it also affects the CD8 memory response by suppressing the expression of IL-7R, which is known to be important for the survival of these cells." (PMID 36883950, 2023). "Surprisingly, data from this study found that not only were there more effector memory cells in Inf and CLInf patients, these cells had a higher mean expression of IL-7Rα (CD127), a finding that differs from what has been seen in chronic viral infections in humans and in mice." (PMID 21559422, 2011).